CYP3A4 (cytochrome P450 family 3 subfamily A member 4)
Description:
A cytochrome P450 monooxygenase involved in the metabolism of sterols, steroid hormones, retinoids and fatty acids. Mechanistically, uses molecular oxygen inserting one oxygen atom into a substrate, and reducing the second into a water molecule, with two electrons provided by NADPH via cytochrome P450 reductase (NADPH--hemoprotein reductase). Catalyzes the hydroxylation of carbon-hydrogen bonds. Exhibits high catalytic activity for the formation of hydroxyestrogens from estrone (E1) and 17beta-estradiol (E2), namely 2-hydroxy E1 and E2, as well as D-ring hydroxylated E1 and E2 at the C-16 position. Plays a role in the metabolism of androgens, particularly in oxidative deactivation of testosterone. Metabolizes testosterone to less biologically active 2beta- and 6beta-hydroxytestosterones. Contributes to the formation of hydroxycholesterols (oxysterols), particularly A-ring hydroxylated cholesterol at the C-4beta position, and side chain hydroxylated cholesterol at the C-25 position, likely contributing to cholesterol degradation and bile acid biosynthesis. Catalyzes bisallylic hydroxylation of polyunsaturated fatty acids (PUFA). Catalyzes the epoxidation of double bonds of PUFA with a preference for the last double bond. Metabolizes endocannabinoid arachidonoylethanolamide (anandamide) to 8,9-, 11,12-, and 14,15-epoxyeicosatrienoic acid ethanolamides (EpETrE-EAs), potentially modulating endocannabinoid system signaling. Plays a role in the metabolism of retinoids. Displays high catalytic activity for oxidation of all-trans-retinol to all-trans-retinal, a rate-limiting step for the biosynthesis of all-trans-retinoic acid (atRA). Further metabolizes atRA toward 4-hydroxyretinoate and may play a role in hepatic atRA clearance. Responsible for oxidative metabolism of xenobiotics. Acts as a 2-exo-monooxygenase for plant lipid 1,8-cineole (eucalyptol). Metabolizes the majority of the administered drugs. Catalyzes sulfoxidation of the anthelmintics albendazole and fenbendazole. Hydroxylates antimalarial drug quinine. Acts as a 1,4-cineole 2-exo-monooxygenase. Also involved in vitamin D catabolism and calcium homeostasis. Catalyzes the inactivation of the active hormone calcitriol (1-alpha,25-dihydroxyvitamin D(3)).
Synonyms: CYP3A3; CP33; CP34; CYP3A; CYPIIIA3; CYPIIIA4; HLP; NF-25; P450C3; P450PCN1; VDDR3
Tractability: Small molecule: an approved drug acts on it; a structure with a bound ligand is known; a high-quality ligand is known; it has a high-quality binding pocket; it belongs to a druggable protein family. Antibody: UniProt predicts a signal peptide or a membrane-spanning region. PROTAC: UniProt records ubiquitination sites on it; ubiquitination databases record sites on it; its protein half-life has been measured; a small molecule that binds it is known.
Target class: Cytochrome P450; Cytochrome P450 family 3A; Cytochrome P450 family 3; Cytochrome P450 3A4; Enzyme
Chemical probes: ML368, PD080805, PD081729, PD084955, PD085038, itraconazole
Safety:
Unwanted effects reported when the protein is acted on. In parentheses: how it was acted on, where the effect was seen, and who reports it.
acute cellular rejection (source: ClinPGx)
adverse events (source: ClinPGx)
alopecia (source: ClinPGx)
clearance of docetaxel (source: ClinPGx)
endometrial cancer following tamoxifen treatment (source: ClinPGx)
infusion-related reaction (source: ClinPGx)
longer period before chemotherapy-induced ovarian failure (source: ClinPGx)
neurotoxicity (source: ClinPGx)
opioid use disorder (source: ClinPGx)
opioid withdrawal symptoms (source: ClinPGx)
opioid withdrawal symptoms and side effects (source: ClinPGx)
respiratory depression (source: ClinPGx)
shorter period of time before chemotherapy-induced ovarian failure (source: ClinPGx)
side effects (source: ClinPGx)
side effects and opioid withdrawal symptoms (source: ClinPGx)
transplant rejection (source: ClinPGx)
Gene: Protein-coding gene on chromosome 7 (99,756,959 to 99,784,274, reverse strand). Ensembl gene ENSG00000160868.
Subcellular location: Endoplasmic reticulum membrane; Microsome membrane
Subcellular location (Human Protein Atlas): Cytosol; Vesicles
Pathways (Reactome):
Metabolism: Aflatoxin activation and detoxification; Biosynthesis of maresin-like SPMs; Phase I - Functionalization of compounds; Xenobiotics
Drug ADME: Aspirin ADME; Atorvastatin ADME; Prednisone ADME
Gene Ontology:
Molecular function: 1,8-cineole 2-exo-monooxygenase activity; 1-alpha,25-dihydroxyvitamin D3 23-hydroxylase activity; anandamide 11,12 epoxidase activity; anandamide 14,15 epoxidase activity; anandamide 8,9 epoxidase activity; caffeine oxidase activity; enzyme binding; estrogen 16-alpha-hydroxylase activity; estrogen 2-hydroxylase activity; iron ion binding; monooxygenase activity; oxidoreductase activity; oxidoreductase activity, acting on paired donors, with incorporation or reduction of molecular oxygen, reduced flavin or flavoprotein as one donor, and incorporation of one atom of oxygen; protein binding; quinine 3-monooxygenase activity; retinoic acid 4-hydroxylase activity; steroid binding; steroid hydroxylase activity; testosterone 6-beta-hydroxylase activity; vitamin D 24-hydroxylase activity; vitamin D3 25-hydroxylase activity; oxygen binding; arachidonate 14,15-epoxygenase activity; heme binding; oxidoreductase activity, acting on paired donors, with incorporation or reduction of molecular oxygen
Biological process: alkaloid catabolic process; estrogen metabolic process; lipid hydroxylation; monoterpenoid metabolic process; oxidative demethylation; retinoic acid metabolic process; retinol metabolic process; steroid catabolic process; steroid metabolic process; vitamin D catabolic process; vitamin D metabolic process; xenobiotic catabolic process; xenobiotic metabolic process; aflatoxin metabolic process; lipid metabolic process; long-chain fatty acid biosynthetic process; calcitriol biosynthetic process from calciol; cholesterol metabolic process; fatty acid metabolic process
Cellular component: cytoplasm; endoplasmic reticulum membrane; intracellular membrane-bounded organelle
Genetic constraint (gnomAD): Loss-of-function variants: 31 observed, 51.13 expected, observed/expected ratio (o/e) 0.61, 90% interval 0.46 to 0.82. The upper end of that interval is the gene's LOEUF score, 0.82, which puts it in group 3 of 6, group 1 being the genes least tolerant of losing a copy. Missense variants: 453 observed, 567.8 expected, observed/expected ratio (o/e) 0.8, 90% interval 0.74 to 0.86. Synonymous variants: 164 observed, 198.98 expected, observed/expected ratio (o/e) 0.82, 90% interval 0.73 to 0.94.
Homologues: Orthologues: chimpanzee CYP3A4 (96% identical), dog CYP3A26 (80% identical), dog CYP3A12 (80% identical), dog CYP3A26 (77% identical), rat Cyp3a9 (77% identical), pig CYP3A29 (76% identical), mouse Cyp3a13 (75% identical), mouse Cyp3a11 (73% identical), rat Cyp3a23-3a1 (72% identical), guinea pig Cyp3a14 (71% identical), mouse Cyp3a41a (71% identical), mouse Cyp3a41b (71% identical), and 17 more. Paralogues in human: CYP3A7 (88% identical), CYP3A5 (84% identical), CYP3A43 (76% identical).
Diseases named in the same sentence as CYP3A4 in open-access papers:
CYP3A4 is named in the same sentence as 379 diseases in open-access papers, as found by Europe PMC text mining. Sharing a sentence is not in itself a finding about the gene and the disease. The quoted sentences say what the papers report.
breast carcinoma (98 papers, 2004 to 2026). "We found that the T allele of rs2242480 within the CYP3A4 gene and interaction between rs2242480 and obesity were associated with an increased risk of breast cancer." (PMID 41242742, 2025). "The purpose of this study was to evaluate the impact of four single nucleotide polymorphisms (SNPs) of CYP3A4 gene, the SNP-SNP and gene-environment interactions on the susceptibility to breast cancer in Chinese women." (PMID 41242742, 2025). "Logistic regression was used to explore the relationship between four SNPs of CYP3A4 gene and the risk of breast cancer." (PMID 41242742, 2025). "In this study, we found that rs2242480 within CYP3A4 gene was significantly associated with increased breast cancer risk." (PMID 41242742, 2025). "The CYP3A4 polymorphism is significantly associated with early onset of puberty, which increases the risk of breast cancer." (PMID 41242742, 2025). "In the future, we suggest that further studies should be performed to explore other SNPs in CYP3A4 or investigating other gene-environment interactions contributing to breast cancer risk." (PMID 41242742, 2025). "In this study, we also performed haplotype analysis to verify the influence of CYP3A4 gene four SNPs on breast cancer risk." (PMID 41242742, 2025). "In conclusion, we found that the T allele of rs2242480 within CYP3A4 gene, their interaction between rs2242480 and obesity were all associated with increased breast cancer risk." (PMID 41242742, 2025). "We found that breast cancer patients had higher frequencies for rs2242480- CT/TT genotypes and rs2242480- T allele of CYP3A4 gene than controls." (PMID 41242742, 2025). "inactivates cyclophosphamide via conversion to dechloroethylcyclophosphamide, and breast cancer patients showed that many CYP3A4 variant polymorphisms are more prevalent in African Americans compared with Caucasians." (PMID 37150853, 2023). "For instance, in breast cancer patients, CYP3A4, CYP3A5, and CYP2B6 polymorphisms were more prevalent in African Americans compared with Caucasians." (PMID 37150853, 2023). "Overexpression of CYP3A4 in a cancerous tissue compared to the normal tissue in most cases correlates with predisposition to breast cancer and ovarian cancer." (PMID 36359206, 2022). "In patients with advanced recurrent breast cancer treated with everolimus and exemestane, the blood everolimus concentration in patients with the CYP3A4*22 allele was significantly higher than that in patients without the *22 allele." (PMID 36188563, 2022). "The CYP3A4 epoxygenase, responsible for the production of EETs, is overexpressed in breast cancer and is linked with the initiation and progression of breast cancer." (PMID 36359206, 2022). "For example, THE TT genotype of CYP3A4 polymorphism is associated with increased risk of breast cancer." (PMID 35096840, 2021). "DMI—a component of the trastuzumab–DMI conjugate used in the treatment of high-risk early stage and metastatic HER-2-positive breast cancer, is metabolised by CYP3A4 and to a lesser extent by CYP3A5." (PMID 33809117, 2021). "The presence of the alternative allele has been previously associated with increased ovarian toxicity in breast cancer survivors receiving cyclophosphamide as part of the treatment regimen and in vitro with increased CYP3A4 expression." (PMID 34572825, 2021). "Another interesting point of discussion is the possibility that SNPs of other CYP isoforms, such as CYP3A4*22, which leads to reduced drug metabolising activity of CYP3A4, are also associated with symptoms such as hot flashes among breast cancer patients." (PMID 34006247, 2021). "In contrast, carrying the CYP3A4*1B allele has also been associated with poorer survival in breast cancer patients receiving cyclophosphamide-containing therapy." (PMID 34572825, 2021). "In breast cancer, Murray and colleagues found high expression of CYP3A4 was associated with a poor prognosis." (PMID 34257549, 2021).
breast carcinoma (continued). "A similar study also reported that breast cancer patients harbouring CYP3A4*22 had lower tendency to develop of tamoxifen-associated hot flashes." (PMID 30914849, 2018). "In the present clinical, cross-sectional case-control study, we have evaluated the potential relationship of the CYP3A4 gene polymorphism with breast cancer." (PMID 30336495, 2018). "The aim of the present study was to evaluate the association between the CYP3A4*1B gene polymorphism (rs2740574) and the risk of developing breast cancer." (PMID 30336495, 2018). "Genetic polymorphism in the recently described CYP3A4*22 has been shown to influence the efficacy of tamoxifen in breast cancer patients." (PMID 30914849, 2018). "This study aimed to analyze the association of genetic polymorphisms in the CYP1A2 and CYP3A4 genes with clinicopathological features, protein expression and prognosis of breast cancer in the northern Chinese population." (PMID 28418906, 2017). "Additionally, studies had noted an increased expression of CYP3A4 in breast cancer cells, which was implicated in processes like cell growth, blood vessel formation, and cellular movement, partly through the production of substances like 11,12- EET." (PMID 41242742, 2025). "Although, T allele of rs2242480 within CYP3A4 could influence breast cancer risk, this effect could be influenced by some environmental factors, such as obesity." (PMID 41242742, 2025). "Therefore, exploring the impact of CYP3A4 gene polymorphism on the risk of breast cancer was of great clinical significance." (PMID 41242742, 2025). "Previous studies have shown that inheriting the CYP3A4*1B allele may increase susceptibility to early-onset menarche, which is a known risk factor for breast cancer." (PMID 37737478, 2023). "Similarly, CYP3A4 upregulation has been established in several breast cancer tumors and its expression levels are associated with docetaxel resistance." (PMID 32581794, 2020). "Given this association between WT1 and CYP3A4 expression in breast cancer, we decided to investigate whether the tumour levels of WT1 can be used to predict the response of breast cancer patients to docetaxel." (PMID 28345629, 2017). "However, more in-depth studies are still needed to perform in different ethnicities in order to validate the associations between genetic polymorphisms in the CYP1A2 and CYP3A4 genes and breast cancer to reveal underlying molecular mechanism." (PMID 28418906, 2017). "However, to date, lack of studies involving the effect of single nucleotide polymorphisms (SNPs) in the CYP1A2 and CYP3A4 genes on the prognosis and survival of patients with breast cancer." (PMID 28418906, 2017). "Additionally, in the present study, there was lack of significant associations between protein expression of CYP1A2 and CYP3A4 in breast cancer tissues and OS." (PMID 28418906, 2017). "In conclusion, this study demonstrates that among women receiving adjuvant chemotherapy for breast cancer, a polymorphism in the cyclophosphamide-metabolizing enzyme CYP3A4 independently contributes to outcomes from cyclophosphamide-based adjuvant breast cancer chemotherapy." (PMID 20459744, 2010). "Related studies have shown that the expression of CYP3A4 is negatively correlated with the sensitivity of breast cancer patients to paclitaxel drugs in neoadjuvant chemotherapy, which may be related to changes in bioavailability caused by the interaction of CYP3A and P-gp." (PMID 34502549, 2021). "In this study, we analyzed 4493 premenopausal women with early‐stage estrogen‐receptor breast cancer to see how taking tamoxifen with certain enzyme‐inhibiting drugs (CYP2D6, CYP2C19, and CYP3A4 inhibitors) affected the risk of cancer recurrence." (PMID 40364655, 2025). "The CYP3A4 gene is located in the Cytochrome P450 gene cluster on chromosome 7q21.1 and plays an important role in the pathogenesis of breast cancer." (PMID 41242742, 2025).
breast carcinoma (continued). "For instance, erythromycin, a moderate CYP3A4 inhibitor, was tested for its effect on the pharmacokinetics of palbociclib, a standard breast cancer treatment." (PMID 40723371, 2025). "For example, CYP3A4 has been reported to increase the growth of breast cancer by facilitating the nuclear translocation of p-STAT3 partially through the synthesis of (±)-14,15-epoxyeicosatrienoic acid (EET)." (PMID 39754188, 2025). "In another study focusing on locally advanced breast cancer patients, those with low circulating CYP3A4 mRNA levels showed higher response rates to docetaxel compared to patients with elevated CYP3A4 mRNA levels (p < 0.01)." (PMID 39598531, 2024). "Carbon Monoxide can suppress the levels of CYP3A4 to enhance the sensitivity of human breast cancer cells to Paclitaxel." (PMID 38215156, 2024). "To determine if KCZ functions through CYP3A4 or AR in our combination treatment studies, we evaluated target availability in normal and breast cancer cell lines." (PMID 39768178, 2024). "CYP3A4 is also required for tumor formation in ER+HER2− breast cancer because this enzyme suppresses autophagy, in part by inhibiting AMPK (AMP-activated protein kinase) activation." (PMID 36359206, 2022). "This notion is supported by the results of a study on breast cancer cell lines in which 8,9-, 11,12-, and 14,15-EETs are synthesized with the participation of highly enzymatically active CYP3A4." (PMID 36359206, 2022). "Studies report that certain polymorphic forms of CYP enzymes such as CYP3A4 promote the rapid clearance of docetaxel from the bloodstream and lowers efficiency of cyclophosphamide in breast cancer." (PMID 35902379, 2022). "A study on tamoxifen-resistant breast cancer revealed that CYP3A4 expression and its epoxide product, 11,12-EET, are upregulated in tamoxifen-resistant MCF-7 cells (TAMR-MCF-7) compared to control MCF-7 cells." (PMID 36359206, 2022). "Taken together, breast cancer drugs commonly target CYP3A4 and other genes of the androgen and estrogen synthesis and metabolism pathway." (PMID 35215292, 2022). "This study critically discusses the latest data about the role of CYP3A4, CYP2D6, and ABCB1 gene polymorphism in the regulation of doxorubicin’s effects in breast cancer patients." (PMID 36358854, 2022). "CYP3A4 is necessary for tumor formation in ER+HER2− breast cancer because this enzyme suppresses autophagy, in part by inhibiting AMPK activation." (PMID 36359206, 2022). "Increased docetaxel-induced adverse events were also observed in breast cancer patients who were CYP3A4*22 carriers and CYP3A5*3 homozygotes." (PMID 35174070, 2021). "This study confirmed the safety and feasibility of using the Inje cocktail to assess the in vivo activity of CYP2C9, CYP2C19, CYP2D6, and CYP3A4 in women receiving chemotherapy for breast cancer (BC)." (PMID 33707475, 2021). "A very low level expression of CYP2C9 and CYP3A4 was observed by RT-PCR in a similar study conducted in a set of 40 breast cancer and adjacent normal tissues." (PMID 33809117, 2021). "In 2001, Schmidt and colleagues identified the presence of CYP3A4 in breast cancer microsomes which aided the metabolism and activation of the CPA prodrug analogue ifosfamide." (PMID 33809117, 2021). "A study on breast carcinomas has revealed the overexpression in cancer tissues of CYP3A4 and CYP2C9." (PMID 32883002, 2020). "Frequency of CYP3A4*1B, CYP3A5*3 and UGT1A4*2 SNPs in 126 Croatian breast cancer (BC) patients and possible association with anastrozole-induced undesirable side effects were analyzed." (PMID 32456253, 2020). "In vitro studies have shown that human prostate cancer (DU-145) and breast cancer (MCF-7) cells lines indeed express a higher amount of CYP3A4 protein in response to treatment with docetaxel." (PMID 31309254, 2019). "Later, breast cancer tissue obtained from a larger trial in 42 patients who underwent docetaxel treatment as adjuvant chemotherapy after surgery was analyzed for CYP3A4 expression using IHC." (PMID 31309254, 2019).